TRPM8 (transient receptor potential cation channel subfamily M member 8)
Diseases named in the same sentence as TRPM8 in open-access papers (continued):
Sharing a sentence is not in itself a finding about the gene and the disease.
fibrosis (2 papers, 2018 to 2022). the formation of excess fibrous connective tissue in an organ or tissue in a reparative or reactive process. "In the bleomycin-induced fibrosis model, 23.5% (4/17) of TRPM8 positive neurons expressed TLR2, 18.2% (4/22) of TRPV1 neurons expressed TLR2, and 44.4% (4/9) of TRPA1 neurons expressed TLR2 in the DRG." (PMID 29518161, 2018). "In the bleomycin-induced fibrosis model, 16.6% (1/6) of TRPM8 positive neurons expressed TLR2, 31.5% (6/19) of TRPV1 neurons expressed TLR2, and 12.5% (1/8) of TRPA1 expressed TLR2 in nodose/jugular ganglion." (PMID 29518161, 2018). "50% (3/6) of TRPM8 positive neurons expressed TLR5, 68.4% (13/19) of TRPV1 neurons expressed TLR5 and 62.5% (5/8) of TRPA1 expressed TLR5 in nodose/jugular ganglion in bleomycin induced fibrosis model." (PMID 29518161, 2018). "In DRG neurons, 41.2% (7/17) of TRPM8 positive neurons expressed TLR5, 59.1% (13/22) of TRPV1 neurons expressed TLR5 and 44.4% (4/9) of TRPA1 neurons expressed TLR5 in the bleomycin-induced fibrosis model." (PMID 29518161, 2018).
leukaemia (2 papers, 2021 to 2024). "Tegaserod maleate exhibits strong anti-AML effects by targeting TRPM8, This demonstrates that TRPM8 is a regulator of leukemia occurrence and has the potential to treat AML as a novel prognostic factor." (PMID 39027429, 2024). "In this regard, integrated methylome, transcriptome, and epigenetic analysis showed that the expression level of many genes is dysregulated in paediatric leukaemia, and among them, the presence of TRPC1, TRPC4, TRPC3, TRPM2, TRPM4, and TRPM8 also stands out." (PMID 34065398, 2021).
lung adenocarcinoma (2 papers, 2020 to 2021). A carcinoma that arises from the lung and is characterized by the presence of malignant glandular epithelial cells. "The quantification of TRPM8 expression in a clinical study with more than 100 human lung adenocarcinoma samples, correlated channel levels with clinical characteristics and prognosis, with high-expression levels of TRPM8 acting as a tumor suppressor, and low levels associated to poor prognostics." (PMID 34445208, 2021). "TRPM8 is overexpressed in lung adenocarcinoma, and TRPM8 expression is negatively correlated with patient survival according to the TCGA and PROGgene databases 36,37." (PMID 32929340, 2020).
metastatic disease (2 papers, 2020 to 2023). "Other studies revealed higher TRPM7 and TRPM8 staining in metastatic tumors than in non-metastatic tumors, which was confirmed by qPCR for TRPM8." (PMID 33178018, 2020). "TRPM8 expression predicts aggressive behavior with early metastatic disease and adverse prognoses." (PMID 37240443, 2023).
metastatic melanoma (2 papers, 2018 to 2026). A melanoma that has spread from its primary site to another anatomic site. "TRPM8 is significantly overexpressed in metastatic melanoma, as compared with the normal counterparts." (PMID 41688418, 2026). "Since TRPM8 activation has an opposing effect on TRPV1 activity, targeting TRPM8 may provide an effective alternative to suppress metastatic melanoma progression without side effects." (PMID 30483120, 2018).
oral squamous cell carcinoma (2 papers, 2015 to 2024). "Menthol enhances the invasion of oral squamous cell carcinoma cells, while TRPM8 antagonists inhibit this invasion by blocking both menthol-induced and inherent TRPM8 activity." (PMID 39759147, 2024). "Consistent with its pro-migratory role, menthol enhances the ability of cell migration and invasion by potentiating MMP-9 activity in oral squamous cell carcinoma; these effects were suppressed by the TRPM8 antagonist RQ-00203078." (PMID 26512697, 2015).
osteoarthritis (2 papers, 2021 to 2023). A noninflammatory degenerative joint disease occurring chiefly in older persons, characterized by degeneration of the articular cartilage, hypertrophy of bone at the margins and changes in the synovial membrane. "The exception was represented by patient 6, in whom the expression of TRPV4 and TRPM8 channels was similar to control tissue and TRPA1, TRPV1, and TRPV2 were expressed, although at a lower level, also in the tissue used as control (probably due to an initial degree of osteoarthritis in this tissue)." (PMID 32955611, 2021).
ovarian carcinoma (2 papers, 2025 to 2026). A malignant neoplasm originating from the surface ovarian epithelium. "For example, TrpV4, TrpC7, and several TrpM family members (TrpM2, TrpM4, TrpM8) are upregulated in ovarian cancer, where their expression negatively correlates with patient prognosis." (PMID 41557739, 2026).
peripheral nerve injury (2 papers, 2012 to 2024). Injury to a peripheral nerve. "It was recently shown that both peripheral and central activation of TRPM8 could produce an analgesic effect that specifically reverses the sensitization of behavioral reflexes elicited by peripheral nerve injury." (PMID 23192000, 2012).
rheumatoid arthritis (2 papers, 2019 to 2023). A chronic, systemic autoimmune disorder characterized by inflammation in the synovial membranes and articular surfaces. "TRPM8 has been studied in rat models of rheumatoid arthritis, but our study is the first to show TRPM8 expression in human OA chondrocytes." (PMID 37373205, 2023). "According to research, TRP channels have become drug targets for the treatment of RA as there are multiple TRP channels in rheumatoid arthritis synovial fibroblasts, including TRPV1, TRPA1, TRPC5, TRPM3, TRPM7, and TRPM8." (PMID 30792744, 2019).
Sepsis (2 papers, 2022). Sepsis is defined as life-threatening organ dysfunction caused by a dysregulated host response to infection. "Thus, the modulatory effect of menthol, and possibly other TRPM8 agonists, on Bcl2 expression and function, and its effect on the prognosis of sepsis is intriguing and needs further investigation." (PMID 35814769, 2022). "Thus, it would be of interest to design future studies to further explore the role of TRPM8 and its potential significance in novel anti-sepsis modalities." (PMID 36120368, 2022).
acute myeloid leukemia (1 paper, 2026). Acute myeloid leukemia (AML) is a group of neoplasms arising from precursor cells committed to the myeloid cell-line differentiation. "A current study on acute myeloid leukemia (AML) highlighted a relationship between TRPM8 and CREB, which indicated a regulative role of TRPM8 on CREB." (PMID 41474182, 2026).
bone cancer (1 paper, 2023). A primary or metastatic malignant neoplasm affecting the bone or articular cartilage. "In addition, overexpression of TRPM8 channels has been demonstrated in gastric, colon, and bone cancers, with a higher expression in patients with metastases." (PMID 37033630, 2023). "In bladder, breast, and bone cancer, it was reported that TRPM8 modulates AKT/GSK-3β signaling." (PMID 37033630, 2023).
brain tumor (1 paper, 2017). "In brain tumors the cold sensor TRPM8 is not exposed to low temperature, which is required to activate the channel in peripheral neurons." (PMID 29221175, 2017).
breast tumors (1 paper, 2020). "TRPM8 is expressed in human breast tissue and its expression is increased in breast tumors; therefore, we aimed to test the specific role of TRPM8." (PMID 33020304, 2020).
bronchitis (1 paper, 2022). An acute or chronic inflammatory process affecting the bronchi. "As a terpenoid, menthol can bind to TRPM8 and has been approved for the treatment of bronchitis and rhinitis." (PMID 36389722, 2022).
channelopathy (1 paper, 2024). Channelopathies are a group of diseases caused by the dysfunction of ion channel subunits or their interacting proteins. "Yet, so far, there is no deleterious mutation in TRPM8 is known that can cause “channelopathy”, and at the same time, all these variants are transmissible to the next generation, suggesting that probably all these variations are tolerable in nature." (PMID 39150496, 2024).
Cirrhosis (1 paper, 2022). A chronic disorder of the liver in which liver tissue becomes scarred and is partially replaced by regenerative nodules and fibrotic tissue resulting in loss of liver function. "Clinicopathological analysis showed that TRPM8 expression was upregulated in tissue samples from cirrhosis patients and fibrotic mice." (PMID 35525986, 2022). "Our results have also shown S100A9 expression was significantly elevated in serum samples from cirrhosis patients compared to healthy donors, as well as a significant reduction in liver samples from CCl4- or BDL-treated TRPM8−/− mice." (PMID 35525986, 2022).
cystitis (1 paper, 2021). Inflammation of the urinary bladder. "Earlier work provided evidence for the role of sensory TRP channels in bladder hyperreactivity during cystitis (TRPV1 and TRPA1), the detection of noxious stimuli in the bladder (TRPA1), and cold-induced bladder reflexes (TRPM8)." (PMID 35008533, 2021).
dermatitis (1 paper, 2025). An inflammatory process affecting the skin. "To further determine its selectivity, we tested the inhibition rate of fluoxetine on other dermatitis-related TRP channels transiently expressed in HEK293T cells, such as TRPV1, TRPV4, TRPA1, and TRPM8." (PMID 40699677, 2025). "Previous research has shown that its activation reduces scratching and inflammatory markers, yet there is a lack of studies on inhibiting TRPM8 in dermatitis." (PMID 40699677, 2025).
esophagitis (1 paper, 2024). An acute or chronic inflammatory disease affecting the esophageal wall. "By employing highly selective agonists and inhibitors, alongside assessing TRPM8’s potential in ameliorating esophagitis, a deeper understanding of TRPM8’s role in esophageal function can be achieved." (PMID 39062591, 2024).
focal epilepsy (1 paper, 2021). A seizure caused by a localized disorder. "In conclusion, TRPM8 agonist may be the basis for the development of new drug treatments for patients with focal epilepsy." (PMID 34658898, 2021).
ischemia (1 paper, 2024). A hypoperfusion of the BLOOD through an organ or tissue caused by a PATHOLOGIC CONSTRICTION or obstruction of its BLOOD VESSELS, or an absence of BLOOD CIRCULATION. "Additional research has demonstrated that TRPM2, TRPM6, TRPM7, and TRPM8 may impact hepatic ischemia-reperfusion injury, with TRPM2 knockout exhibiting a reduction in such injury through the activation of autophagy and inhibition of autophagy-negative regulation of the NLRP3 inflammasome pathway." (PMID 38255767, 2024).
liver diseases (1 paper, 2024). "In summary, TRPM8 consistently exerts a negative impact on liver inflammation, tumors, fibrosis, and beyond, underscoring its potential as a viable target for the future development of TRPM8-targeted therapeutic interventions for liver diseases to mitigate adverse effects." (PMID 39062591, 2024).
lymphangioleiomyomatosis (1 paper, 2025). A multifocal neoplasm with perivascular epithelioid cell differentiation affecting almost exclusively females of child-bearing age. "Plasma concentrations of rapamycin in patients on systemic drug regimens following organ transplantation or for the treatment of lymphangioleiomyomatosis or cancer rarely exceed 100 nM, rendering it unlikely that substantial rapamycin-induced TRPM8 activation would occur in these subjects." (PMID 41025355, 2025).
malignant glioma (1 paper, 2021). A grade III or grade IV glioma arising from the central nervous system. "As emphasized above for TRPM8, there is still a long road before these types of compounds targeting TRPC5 will enter clinics to treat malignant glioma patients." (PMID 34458247, 2021).
metastatic cancer (1 paper, 2022). A carcinoma which has spread from the original site of growth to another anatomic site. "The complete characterization of the molecular mechanisms by which TRPM8 performs its anti-metastatic function could provide new and important insights into view, of the possible and successful use of TRPM8 as a pharmaceutical target in the treatment of advanced stages of metastatic cancer." (PMID 35565390, 2022).
metastatic colorectal cancer (1 paper, 2024). "With an in vitro approach, we demonstrated that the administration of iPolyP induces the expression of PCNA in Caco-2 and in SW620, non-metastatic and metastatic colorectal cancer cell lines, respectively, without altering the TRPM8 levels." (PMID 39409946, 2024).
Nausea (1 paper, 2018). A sensation of unease in the stomach together with an urge to vomit. "THCA is a TRPA1 partial agonist, and TRPM8 antagonist which may underlie a potential role in analgesia, and has been shown to have anti-inflammatory and anti-nausea properties." (PMID 29797104, 2018).
osteoporosis (1 paper, 2021). A condition of reduced bone mass, with decreased cortical thickness and a decrease in the number and size of the trabeculae of cancellous bone (but normal chemical composition), resulting in increased fracture incidence. "TRPM8 inhibitor, namely AMTB at very low concentrations could provide an opportunity for their therapeutic use in enhancing osteogenesis and could be relevant for treatment of different bone-related disorders such as osteoporosis where more bio-mineralization is required." (PMID 33580126, 2021).
pancreatic ductal adenocarcinoma (1 paper, 2023). An infiltrating adenocarcinoma that arises from the epithelial cells of the pancreas. "Both TRPM7 and TRPM8 proteins are absent in normal pancreatic ducts, but are present in a subset of pancreatic ductal adenocarcinoma patients, where TRPM8 expression heralds adverse outcomes." (PMID 37240443, 2023).
Polyuria (1 paper, 2026). An increased rate of urine production. "The hypothesis label 'dual hormone suppression' (attenuated nocturnal AVP signal plus estradiol decline) may provide a mechanistic substrate for cold-exacerbated nocturnal polyuria, while an estrogen-TRPM8 axis may amplify cold-evoked urgency." (PMID 41829995, 2026).
prostate adenocarcinoma (1 paper, 2022).
psoriasis (1 paper, 2026). An autoimmune condition characterized by red, well-delineated plaques with silvery scales that are usually on the extensor surfaces and scalp. "Growing evidence suggests the involvement of multiple TRP subtypes in the pathogenesis of psoriasis, including altered expression of vanilloid subtypes, such as TRPV1, TRPV3, TRPV4, TRPV6, the canonical TRPC6, and melastatin TRPM8 in patients." (PMID 41689746, 2026).
steatosis (1 paper, 2025). Increased lipid within the cytoplasm of cells. "Furthermore, concentration‐dependent inhibition of steatosis and fibrosis was replicated for selumetinib (MAP2K1 inhibitor), MK‐2206 (AKT inhibitor), and PF‐05105679 (TRPM8 inhibitor)." (PMID 39605182, 2025).
Stroke (1 paper, 2022). Sudden impairment of blood flow to a part of the brain due to occlusion or rupture of an artery to the brain. "Our results suggested that activation of peripheral TRPM8 expressed in the derma tissue of limbs with sufficient concentration of menthol is beneficial to stroke recovery." (PMID 35897101, 2022). "The present study aimed to explore whether activation of peripheral TRPM8 by administering menthol treatment may effectively limit neurological deficits following cerebral ischemia in a mouse middle cerebral artery occlusion (MCAO) model of stroke." (PMID 35897101, 2022). "No research has as yet described the role of TRPM8 in stroke." (PMID 35897101, 2022).
testicular cancer (1 paper, 2022). A primary or metastatic malignant neoplasm that affects the testis. "Cisplatin induction of TRPM8 is reported to lead to calcium influx in testicular cancer, reducing tumor growth." (PMID 35847920, 2022).
tongue cancer (1 paper, 2023). A malignant neoplasm affecting the tongue. "Functional TRPM8 expression was reported in two human SQCC cell lines derived from tongue cancer, HSC3 and HSC4." (PMID 37240443, 2023).
viral infection (1 paper, 2016). "This is inconsistent with the previous study that demonstrated functional expression of TRPM8 in immortalized HCE cells, suggesting the expression of TRPM8 in HCE cells may be sensitive to viral infection and culture conditions." (PMID 27448228, 2016).